STAT3 (signal transducer and activator of transcription 3)
Diseases named in the same sentence as STAT3 in open-access papers (continued):
Sharing a sentence is not in itself a finding about the gene and the disease.
ischemic stroke (continued). "A previous study has shown that JAK2/STAT3 signaling pathways serve an important function in the downstream signal pathway regulation of ischemic stroke‐related inflammatory neuronal damage." (PMID 37786415, 2022). "IL-13 promotes white matter repair and improves neurofunctional outcomes after ischemic stroke by modulating microglia/macrophages via inhibition of STAT3 phosphorylation." (PMID 35578342, 2022). "The mechanism(s) by which IL-13-induced alterations in STAT3 signaling modifies ischemic stroke outcomes remains to be clarified." (PMID 35578342, 2022). "Delayed recanalization after middle cerebral artery occlusion ameliorated ischemic stroke by inhibiting apoptosis via the HGF/c-Met/STAT3/Bcl-2 pathway in rats." (PMID 34421795, 2021). "Reactive oxygen species (ROS) formation after ischaemic stroke activates signal transducer and activator of transcription 3 (STAT3)." (PMID 33924191, 2021). "In conclusion, our data suggest that shLINGO-1 attenuated ischemic injury by negatively regulating NF-KB and JAK2/STAT3 pathways, highlighting a novel therapeutic target for ischemic stroke." (PMID 33830473, 2021). "It's known that both STAT1 and STAT3 are highly expressed in the brain, and reported to involve in the ischemic stroke and cognitive regulation 16-19, 43-44." (PMID 33859760, 2021). "Here, the present study revealed that LINGO-1 shRNA treatment suppressed the activation of the JAK2/STAT3 and NF-κB signaling pathways in both vivo and in vitro ischemic stroke models." (PMID 33830473, 2021). "Taken together, these data indicated that STAT3 play an important role in the pro-angiogenic effect by iMSC-sEV in ischemic stroke." (PMID 32698909, 2020). "Phosphorylated STAT3 decreased significantly in ischemic stroke rats compared to sham rats, and iMSC-sEV dramatically reversed this decrease." (PMID 32698909, 2020). "The results of the present study demonstrated that iMSC-sEV increased STAT3 activation during ischemic stroke, which was accompanied by a reduction in Beclin-1." (PMID 32698909, 2020). "Taken together, our data indicate that iMSC-sEV promote angiogenesis after ischemic stroke, potentially, by inhibiting autophagy, a process that is partially dependent on STAT3 activation." (PMID 32698909, 2020). "SLT mediates neuroinflammation, thereby protecting against ischaemic brain injury by inhibiting astrogliosis and suppressing neuroinflammation via the LCN2-JAK2/STAT3 pathway, providing a new idea for the treatment strategy of ischaemic stroke." (PMID 31565154, 2019). "It is reasonable to assume that argon influences the activation and function of STAT3, which in turn produces an effect on microglia/macrophage polarization, and ultimately leads to behavioral and histological improvements after ischemic stroke." (PMID 31159847, 2019). "Signal transducer and activator of transcription 3 (STAT3) is involved in ischemic stroke and intracerebral hemorrhage and has been a treatment target for experimental ICH." (PMID 30836997, 2019). "LncRNA TCONS_00097976 is connected to angiogenesis-related miR-92b-3p and angiogenesis-related genes Esm1, Angptl2, and Stat3, which have been reported differently expressed in ischemic stroke." (PMID 29516010, 2018). "Expression levels of STAT3 have been shown to be enhanced in reactive microglia cells when the brain suffers focal ischemic injury Aberrantly activated STAT3 has also been reported to involved in the neuroinflammatory injury after ischemic stroke." (PMID 28923114, 2017). "Associated with pJAK3/activated JAK3, we also determined that phosphorylated STAT3 is markedly increased in the ipsilateral cortex after ischemic stroke, and this is reduced with 10 mg/kg decernotinib." (PMID 28790974, 2017). "Total and pJAK3/activated JAK3 and phosphorylated STAT3 levels dramatically increase after ischemic stroke in addition to upregulated IL-21 mRNA." (PMID 28790974, 2017).
ischemic stroke (continued). "Our results indicated that Sino suppresses the neuroinflammation via targeting the astrocytic DRD2/CRYAB/STAT3 pathway in cerebral ischemic model in vivo and in vitro, which sheds some light on a promising therapeutic strategy for ischemic stroke." (PMID 27724964, 2016). "Our study demonstrates that Sino activates astrocytic DRD2 and thereby suppresses neuroinflammation via the CRYAB/STAT3 pathway, which sheds some light on a promising therapeutic strategy for ischemic stroke." (PMID 27724964, 2016). "Of these, the activation of STAT3 and NF-κB plays a predominant role in the neuroinflammatory cascades and secondary cerebral injury after ischemic stroke by controlling the expression of many proinflammatory genes." (PMID 23437066, 2013). "Moreover, the JAK2/STAT3 signaling enhances recovery of neurological function after ischemic stroke." (PMID 40653468, 2025). "Previous studies have demonstrated that STAT3 is a crucial mediator of microglia polarization and inflammatory response, acting as a recognized regulator of inflammatory gene expression and a reliable indicator of ischemic stroke injury." (PMID 37869777, 2024). "It is therefore plausible to speculate that circPTP4A2 can regulate microglial polarization by affecting the cytoplasmic/nuclear translocation of STAT3 and, thus, impacting neuroinflammation in ischemic stroke." (PMID 37869777, 2024). "In vivo and in vitro studies have shown that STAT3 is deactivated in ischemic stroke." (PMID 39403058, 2024). "The results support the hypothesis that EP contributes to alleviating MCAO‐induced neuronal apoptosis, Th17/Treg imbalance, and inflammation via inhibiting the JAK2/STAT3 signaling pathway, indicating its therapeutic potential in ischemic stroke." (PMID 37143406, 2023). "Further studies of silencing STAT3 specifically in MG would provide insight into whether the activation of STAT3 via IFNAR1 signaling is required for IFNβ-mediated modulation of MG phenotypes in ischemic stroke with delayed tPA treatment." (PMID 37063896, 2023). "Our results suggest that interventions aimed at activating endothelial STAT3 in the acute stages of ischemic stroke may be tissue protective, in part via maintenance of barrier integrity." (PMID 36293020, 2022). "Notably, MAPK3, MAPK1, HSP90AA1, STAT3, PIK3R1, PIK3CA, and AKT1 were the main target proteins involved in the pathogenesis of ischemic stroke with Qi deficiency and blood stasis syndrome." (PMID 35401166, 2022). "Mechanistically, IL-13 improved the long-term outcome after ischemic stroke by promoting the polarization of microglia/macrophages toward the anti-inflammatory phenotype at least partially by inhibiting the phosphorylation of STAT3." (PMID 35578342, 2022). "In conclusion, we reported a previously undefined molecular target of IL-13 in the CNS, namely that IL-13 played a neuroprotective role at least partially by inhibiting the activation of STAT3, which has been shown to mediate pro-inflammatory responses in microglia in response to ischemic stroke." (PMID 35578342, 2022). "Our data suggest that ROS-mediated NF-κB inhibition and STAT3 activation are the key pathways for glycogen mobilization-induced neuroprotection and provide a promising metabolic target for brain reperfusion injury in ischemic stroke." (PMID 34645472, 2021). "Our findings indicated that inhibiting AIM2 preserved the BBB integrity after ischemic stroke, at least partially by modulating STAT3 activation and that AIM2 may be a promising therapeutic target for cerebral ischemic stroke." (PMID 34156153, 2021). "Furthermore, STAT3 was also associated with M1 microglia polarization in both an MCAO-induced and a bilateral common carotid arteries stenosis (BcaS)-induced model of ischemic stroke." (PMID 34276530, 2021). "The STAT3 inhibitor stattic was used to examine whether the pro-angiogenic effect of iMSC-sEV on ischemic stroke was related to STAT3-dependent autophagy." (PMID 32698909, 2020).
ischemic stroke (continued). "The role of STAT3 signaling in ischemic stroke requires further exploration." (PMID 32174916, 2020). "iMSC-sEV significantly activated STAT3 after ischemic stroke in vivo and in vitro." (PMID 32698909, 2020). "The present study detected that ischemic stroke decreased STAT3 activation in vivo and in vitro." (PMID 32698909, 2020). "We deemed that STAT3 could regulate the expression in ischemic stroke, so we used WP1066 for further study." (PMID 31827699, 2019). "In order to determine whether pretreatment with a specific inhibitor of JAK2/STAT3 (AG490) would ameliorate the brain damage in ischemic stroke, we administered AG490 prior to tMCAO in Ntg and GET-1 mice." (PMID 31733648, 2019). "Previous studies have demonstrated the key angiogenesis functions of Stat3 in ischemic stroke." (PMID 29516010, 2018). "Thus, TCONS_00097976-miR-92b-3p-Stat3 would be ceRNA mediated ischemia response networks which participated in the regulation of angiogenesis after ischemic stroke." (PMID 29516010, 2018). "Furthermore, increased phosphorylated STAT3 24 h after MCAO has been reported before in other rodent models of ischemic stroke." (PMID 28790974, 2017). "Our findings suggest that postischemic treatment with KRS or KGS prevents ischemic brain injury and neuroinflammation by inhibition of STAT3 and NF-κB activation and has the therapeutic potential for the neuroinflammation-related diseases, such as ischemic stroke." (PMID 23437066, 2013). "STAT3 may inhibit autophagy by reducing Beclin-1 levels in ischemic stroke patients." (PMID 39403058, 2024). "In addition, the small extracellular vesicles secreted by MSCs derived from human iPSCs had the ability to promote angiogenesis and provide protection against brain injury after ischemic stroke by inhibiting signal transducer and activator of transcription 3 (STAT3)-dependent autophagy." (PMID 34135724, 2021). "Therefore, STAT3 and NF-κB have become potential targets for intense drug discovery and development efforts for neuroprotection against neuroinflammation-related diseases, such as ischemic stroke." (PMID 23437066, 2013). "ROC monofactor analysis demonstrated a good performance of HMOX1, STAT3, CYBB, and TLR4 in the diagnosis of ischemic stroke." (PMID 36506580, 2022). "Cryptotanshinone was regarded as the STAT3 and STAT5 regulator for ischemic stroke and chronic myelocytic leukemia." (PMID 36324680, 2022). "In addition, the transcription factor specific protein 1 (SP1), nuclear factor of kappa light polypeptide gene enhancer in B-cells 1 (NF-κB1) and signal transducer and activator of transcription 3 (STAT3) may be key transcription factors in the treatment of ischemic stroke with kaempferol." (PMID 36293548, 2022). "STAT3 activation has been shown to mediate pro-inflammatory responses in microglia in response to ischemic stroke, whereas inhibition of the JAK2-STAT3 pathway has been shown to selectively promote microglia polarization to a beneficial phenotype." (PMID 35578342, 2022). "Therefore, STAT3 may inhibit autophagy via a reduction in Beclin-1 in ischemic stroke." (PMID 32698909, 2020). "Notably, STAT3 is a pivotal mediator of the anti-inflammatory effects of IL-10 also in human macrophages and is among the highly predicted target genes for the dysregulated miRNAs occurring in the peripheral blood mononuclear cells (PBMCs) of ischemic stroke patients." (PMID 31849581, 2019). "Our findings suggest that STAT3 is a potential target for intervention in pathologies where there is hypoxia or OGD, e.g. asphyxiation, tumor pathologies or in ischemic stroke." (PMID 29518129, 2018).
ischemic stroke (continued). "It is well documented that KCND2 upregulates STAT3 in ischemic stroke; therefore, there is speculation whether KCND2 can regulate STAT3 in response to NF‐κB pathway activation, which we will confirm with more follow‐up studies." (PMID 37347147, 2023). "Using PyMOL software, Discovery studio 4.5 client, and Autodock tools 1.5.6 software, the interaction between potential active compounds (Tanshinol A, Tanshinol B, Tanshinone II A and Przewaquinone C) and ischemic stroke related proteins (MMP2, STAT3, TERT, and ESR1) was studied." (PMID 36133785, 2022). "Given that the pro-angiogenic activities of ahNSCs are one of the treatment mechanisms for ischemic stroke, it was determined whether the JAK2/STAT3 signaling pathway is also involved in the pro-angiogenic activities of NSC-CM using endothelial cells (HUVECs)." (PMID 36446389, 2022). "For further verification, potential core targets (STAT3, MMP2, ESR1, TERT, and MMP9 proteins) for ischemic stroke and core active ingredients (Tanshinol A, Tanshinol B, Tanshinone II A, and Przewaquinone C) for Salvia miltiorrhiza Bge. were further verified by molecular docking." (PMID 36133785, 2022). "Here, we found that p‐STAT3 and BDNF levels increased in parallel to HSP70 upregulation, indicating that L‐glutamine‐induced HSP70 was involved in the proliferation of astrocytes by activating p‐STAT3 pathway and promoted the secretion of BDNF after ischemic stroke." (PMID 31218845, 2019). "For instance, AD16 has been shown to mitigate ischemic stroke‐induced brain injury by reducing A1 astrocyte polarization, thereby suppressing neuroinflammation via the downregulation of NF‐κB and Janus Kinase 2 (JAK2)/signal transducer and activator of transcription 3 (STAT3) signaling pathway." (PMID 40130432, 2025). "Moreover, EZH2 may regulate the activation of microglia by activating phosphorylated signal transducer and activator of transcription 3 (STAT3), aggravating the inflammatory response after ischemic stroke." (PMID 35091962, 2022). "LINGO-1 shRNA could ameliorate neurological deficits, reduce brain infarct volume and damage to cerebral cortical neurons in vivo ischemic stroke model, alleviate apoptosis and promote cell proliferation in vitro ischemic stroke model via the NF-κB and JAK2/STAT3 pathway." (PMID 33830473, 2021). "In addition, miR-124 suppresses apoptosis in ischemic stroke via directly targeting and upregulating Bcl2, Bcl-xl, Usp14, JAK/STAT3, and PI3K/AKT/Nrf2 signaling pathways, while other researchers reported that miR-124 promotes neuronal apoptosis through inhibiting iASPP and Ku70 in ischemic stroke." (PMID 31878035, 2019). "Additionally, HSYA may inhibit JAK2-mediated signaling, activating p-JAK2/p-STAT3 expression and subsequently suppressor of cytokine signalling-3 (SOCS-3), which provides negative feedback on p-JAK2/p-STAT3, aiding HSYA’s therapeutic effects on ischemic stroke." (PMID 40843199, 2025).
neuroblastoma (77 papers, 2005 to 2025). Neuroblastoma (NB) is the most common solid, extracranial childhood tumor. "STAT3 inhibition decreased the upregulation of ID1 levels caused by heparin-binding epidermal growth factor (HB-EGF) in neuroblastoma cells." (PMID 38183094, 2024). "Neuroblastoma S‐type cells promote survival of N‐type tumor cells through cell‐to‐cell contact, which is associated with upregulation of p‐STAT3 in N‐type cells." (PMID 33932101, 2021). "In mouse and human neuroblastoma cells, TAMs are found to increase STAT3 activation in neuroblastoma cells, and up-regulates MYC oncogenes, a process associated with IL-6 independent expression." (PMID 33224886, 2020). "Moreover, ectopic expression of miR-323a-3p in neuroblastoma cell lines lead to reduced cell viability, G1-cell cycle arrest and apoptosis, and caused reduced expression of STAT3 because of direct binding of miR-323a-3p to the 3′UTR of STAT3 mRNA." (PMID 37033189, 2023). "Thus, pharmacological inhibition of STAT3 activity in neuroblastoma cell lines harboring ALK gain-of-function mutations results in reduced transcription of MYCN mRNA." (PMID 23889739, 2013). "However, to determine any causal relationship between p55α/p50α expression and STAT3 levels in a neuroblastoma context requires further investigation." (PMID 23597230, 2013). "For example, miR-323a-3p can bind and repress the expression of signal transducer and activator of transcription 3 (STAT3) to inhibit tumour progression in neuroblastoma." (PMID 39736850, 2025). "Low concentrations of MeHg enhance ciliary neurotrophic factor (CNTF)-evoked STAT3 phosphorylation in human neuroblastoma SH-SY5Y and mouse cortical neural progenitor cells (NPCs)." (PMID 40802001, 2025). "We confirmed that Stat3 is a factor that promotes malignant progression and poor prognosis of neuroblastoma." (PMID 39356934, 2024). "This suppression of the Jak2/Stat3 pathway resulted in significant growth inhibition and increased apoptosis in neuroblastoma cells." (PMID 39356934, 2024). "On the other hand, CAFs derived from neuroblastomas have shown that IL-6 activates various signaling pathways, including STAT3, ERK1/2, and STAT1, in tumor cells." (PMID 38606999, 2024). "Considering the role of overactivity of Stat3 signaling in neuroblastoma, the effectiveness of the therapeutic potential of targeting this pathway remains to be revealed." (PMID 39356934, 2024). "Our findings revealed that both agents individually and synergistically inhibit the activation of Jak2 and subsequent phosphorylation of Stat3, a critical transcription factor involved in promoting cell survival and proliferation in neuroblastoma." (PMID 39356934, 2024). "In this study, we demonstrated that NP and DX effectively suppress the proliferation of neuroblastoma cells by targeting the Jak2/Stat3 signaling pathway." (PMID 39356934, 2024). "NP, which can inactivate Jak2/Stat3, can be used as a treatment agent by combining with DX in proliferation pathway in neuroblastoma." (PMID 39356934, 2024). "The aim of this study was to investigate the effects of napabucasin and doxorubicin on suppressing the proliferation of neuroblastoma cells through the Jak2/Stat3 signaling pathway." (PMID 39356934, 2024). "In the scope of the study, vehicle control, DX and NP doses were applied individually and in combination to SH-SY5Y neuroblastoma cells, and IL-6, IL-6-R, Jak2, and Stat3 gene expressions were determined at the end of 48 hours." (PMID 39356934, 2024). "The miR-323a-3p or NC mimics were transfected into neuroblastoma cell lines and the expression levels of STAT3 mRNA and protein were examined by RT-qPCR and western blot analysis, respectively." (PMID 37033189, 2023).